RNY4P3 (RNY4 pseudogene 3)
Synonyms: hY4.F2
Gene: Miscellaneous RNA gene on chromosome 16 (50,098,264 to 50,098,358, forward strand). Ensembl gene ENSG00000202124.
Homologues: Orthologues: chimpanzee Y_RNA (100% identical). Paralogues in human: RNY4 (93% identical), RNY4P7 (92% identical), RNY4P6 (91% identical), Y_RNA (91% identical), RNY4P14 (89% identical), RNY4P10 (88% identical), RNY4P13 (88% identical), RNY4P23 (88% identical), Y_RNA (88% identical), RNY4P19 (87% identical), Y_RNA (87% identical), RNY4P17 (86% identical), and 89 more.